ENSG00000266202 (novel protein)
Gene: Protein-coding gene on chromosome 17 (27,798,806 to 27,893,365, reverse strand). Ensembl gene ENSG00000266202.
Genetic constraint (gnomAD): Loss-of-function variants: 14 observed, 8.37 expected, observed/expected ratio (o/e) 1.67, 90% interval 1.05 to 1.95. That is too few expected variants to judge how well the gene tolerates losing a copy. Missense variants: 88 observed, 81.55 expected, observed/expected ratio (o/e) 1.08, 90% interval 0.91 to 1.29. Synonymous variants: 40 observed, 32.21 expected, observed/expected ratio (o/e) 1.24, 90% interval 0.96 to 1.62.